METTL3 (methyltransferase 3, N6-adenosine-methyltransferase complex catalytic subunit)
Diseases named in the same sentence as METTL3 in open-access papers (continued):
Sharing a sentence is not in itself a finding about the gene and the disease.
pancreatic cancer (continued). "Meanwhile, we found the same results in pancreatic cancer cells, indicating that the E3 ligase activity of TRIM21 is required for METTL3 ubiquitylation." (PMID 40175350, 2025). "Previously, a study revealed that cigarette smoke condensate promoted METTL3 overexpression by inducing hypomethylation of METTL3 promoter and recruitment of the transcription factor NFIC in pancreatic cancer." (PMID 38481809, 2024). "The m6A writer METTL3 was found to be upregulated in gemcitabine-resistant PDAC samples and METTL3 silence sensitized pancreatic cancer cells to chemotherapy." (PMID 36977668, 2023). "To further illuminate the role of DDX23 in METTL3-induced pancreatic cancer progression, we overexpressed DDX23 in PDAC cells depleted of METTL3." (PMID 36977668, 2023). "An identified downstream target of METTL3, DDX23 mRNA, was discovered to be upregulated in pancreatic cancer and predict poor survival, as well as positively correlated with PI3K/Akt pathway." (PMID 36977668, 2023). "Another study indicated that METTL3-mediated m6A methylation decreased the expression of lncRNA DBH-AS1 in pancreatic cancer, while DBH-AS1 increased the sensitivity of pancreatic cancer cells to gemcitabine through the miR-3163/USP44 axis." (PMID 37264402, 2023). "This study will further explore the effects of STM2457, a small-molecule inhibitor of METTL3, on the BANCR expression and m6A methylation of pancreatic cancer cells." (PMID 37998732, 2023). "Specifically, Bcl-2, Claspin, METTL3 and YTHDF3 were identified as the potential targets of celastrol treatment in pancreatic cancer cells." (PMID 38110764, 2023). "Based on this, the aim of our study was to investigate the effect of a highly potent and selective first-in-class catalytic inhibitor of METTL3 (STM2457) on BANCR m6A methylation and its malignant biological behaviors in pancreatic cancer." (PMID 37998732, 2023). "Our results indicate that miR-33a-3p modulates METTL3-mediated m6A-AREG stability and thereby suppresses pancreatic cancer invasion and metastasis." (PMID 37604948, 2023). "It was shown that m6A methyltransferase METTL3 was upregulated in PDAC tissues with gemcitabine resistance, and its knockdown sensitized pancreatic cancer cells to chemotherapy." (PMID 36977668, 2023). "Through the GEO database, it was found that expression of METTL3 and IGF2BP3 in pancreatic cancer tissues were higher than those in adjacent tissues." (PMID 36276112, 2022). "Knockdown of METTL3 or IGF2BP3 significantly reduced the SMS protein expression and inhibited the migration of pancreatic cancer." (PMID 36276112, 2022). "We performed single-cell RNA-sequencing of pancreatic cancer tissue from control (EL1) and METTL3-overexpressing (WTg) mice and bulk RNA-sequencing using murine primary cells cultured from tumors (MPC) derived from pancreatic cancer tissue." (PMID 35773310, 2022). "Survival analysis showed that the expression of METTL3 and IGF2BP3 affected the prognosis of pancreatic cancer patients and that high expression of METTLE/IGF2BP3 can promote the progression of pancreatic cancer." (PMID 36276112, 2022). "In the migration and invasion experiments, interfering with the expression of METTL3 and IGF2BP3 inhibited the migration and invasion of pancreatic cancer." (PMID 36276112, 2022). "To further explore the role of METTL3 and IGF2BP3 in pancreatic cancer, we conducted western blot experiments by transfecting METTL3-siRNA and IGF2BP3-siRNA into PANC-1 and Mia-Paca2." (PMID 36276112, 2022). "Through further exploration, we found that METTL3 and IGF2BP3 can significantly inhibit the migration and invasion of pancreatic cancer cells." (PMID 36276112, 2022). "Previous studies reported that METTL3, METTL14, FTO, ALKBH5 and YTHDF2 play important roles in pancreatic cancer cells." (PMID 34458141, 2021).
pancreatic cancer (continued). "An m6Ascore based on the expression of IGF2BP2, IGF2BP3, KIAA1429, METTL3, EIF3H and LRPPRC is proposed as an indicator of TME status and is instrumental in predicting the prognosis of pancreatic cancer patients." (PMID 34332578, 2021). "An overexpression of METTL3 in the MIA-PaCa-2 and BxPC-3 pancreatic cancer cell lines was involved in pancreatic carcinogenesis and promoted proliferation and invasion of pancreatic cancer cell lines in Xia T’s study." (PMID 34332578, 2021). "METTL3 is overexpressed in PDAC and has been shown to contribute to chemoresistance of pancreatic cancer cells." (PMID 33855021, 2021). "Survival analysis showed that METTL3 serves as a prognostic factor for poor outcomes for CRC, GC, pancreatic cancer, HCC and thyroid carcinoma patients." (PMID 33431045, 2021). "It was demonstrated in pancreatic cancer that cigarette smoke condensate induces hypomethylation of METTL3 promoter and subsequently the recruitment of transcription factor NFIC to induce METTL3 overexpression." (PMID 32854717, 2020). "METTL3 and METTL14 are proposed as novel and promising targets for enhancing chemosensitivity and radiosensitivity of pancreatic cancer cells." (PMID 33029866, 2020). "A previous study reported that METTL3, ALKBH5 and YTHDF2 play important roles in pancreatic cancer cells." (PMID 32843065, 2020). "Western blot also showed that METTL3 METTL14 and WTAP levels were significantly higher in pancreatic cancer samples compared with normal tissue samples." (PMID 32843065, 2020). "Knocking down of METTL3 also significantly inhibited CSC-induced miR-25-3p overexpression in HPDE6-C7 and pancreatic cancer cells." (PMID 31015415, 2019). "Similar to the effect of METTL3 depression, NFIC knockdown also substantially inhibited CSC-induced miR-25-3p overexpression in HPDE6-C7 and pancreatic cancer cells." (PMID 31015415, 2019). "Understanding the role of Mettl3, DDX23, m6A modification, and the PI3K/Akt pathway in gemcitabine resistance provides insights into potential avenues for overcoming this treatment obstacle in pancreatic cancer." (PMID 41517663, 2026). "Besides, we detected the expression of METTL3 and EMP1 in pancreatic cancer samples serially sectioned with IGF2BP3 in Cohort1 and found that EMP1 was also positively correlated with METTL3 and IGF2BP3." (PMID 41285728, 2025). "Additionally, we discovered that METTL3 promotes HMGB1 degradation through a m6A-YTHDF2-dependent pathway, inhibits ferroptosis in pancreatic cancer cells, and confers resistance to gemcitabine treatment." (PMID 40495163, 2025). "In addition, quercetin functions as a selective METTL3 inhibitor, exhibiting an IC50 of 2.73 μM, and demonstrates dose-dependent attenuation of m6A levels in pancreatic cancer cells." (PMID 40986143, 2025). "METTL3 regulated m6A modification, and IGF2BP3 recognized the 3’UTR region of EMP1 mRNA, which could be eliminated by silencing METTL3 in pancreatic cancer cells." (PMID 41285728, 2025). "This promoting effect of METTL3 on VEGFA is also observed in CRC, pancreatic cancer and BLCA." (PMID 39098905, 2024). "Notably, m6A “writer” proteins, namely METTL3 and METTL14, have been identified as dysregulated factors in bladder, gastric, and pancreatic cancers." (PMID 38528591, 2024). "Another study showed that irradiation of pancreatic cancer cells MIA and PaCa-2 in combination with METTL3 knockdown can further enhance cellular radiosensitivity through MAPK cascades, ubiquitin-dependent processes, RNA splicing, and regulation of cellular processes." (PMID 38473842, 2024). "Collectively, our findings indicated that Claspin, Bcl-2, METTL3, and YTHDF3 might be the potential targets of celastrol treatment in pancreatic cancer cells." (PMID 38110764, 2023). "In addition, METTL3 was also reported to promote resistance to chemotherapy, including GEM, 5-fluorouracil, cisplatin, and radiotherapy of pancreatic cancer cells." (PMID 36977668, 2023).
pancreatic cancer (continued). "In pancreatic cancer, absence of METTL3 resulted in increased sensitivity to anticancer treatment, in particular to chemotherapy with gemcitabine, 5-fluoruracil, and platinum." (PMID 35731272, 2023). "This suggested that METTL3 and DBH-AS1 may be involved in the development of gemcitabine resistance in pancreatic cancer." (PMID 37264402, 2023). "Similarly, depletion of METTL3 in pancreas cancer results in higher sensitivity to several common anticancer drugs, such as gemcitabine, 5-FU and DDP in vitro, suggesting METTL3 as a potent target for improving therapeutic efficacy." (PMID 36810281, 2023). "In summary, the findings present here provided in vitro and in vivo evidences demonstrating that downregulation of Bcl-2, Claspin, METTL3 and YTHDF3 was involved in celastrol-induced cellular proliferation inhibition, cell cycle arrest and apoptosis in pancreatic cancer cells." (PMID 38110764, 2023). "Indeed, upregulation of METTL3 increased the MALAT1 level, and downregulation of METTL3 reduced the expression of MALAT1 in pancreatic cancer cells." (PMID 36212476, 2022). "In pancreatic cancer, cigarette smoke condensate leads to hypomethylation of the METTL3 promoter, which promotes the recruitment of the transcription factor NFIC and induces METTL3 overexpression." (PMID 36424383, 2022). "It is speculated that METTL3 may regulate the MAPK cascade and cellular processes, leading to resistance to chemotherapy and radiotherapy in pancreatic cancer cells." (PMID 34246319, 2021). "After treated with gemcitabine, only METTL14 was significantly increased in all six pancreatic cancer cell lines, but not METTL3, WTAP, VIRMA, FTO or ALKBH5." (PMID 34458141, 2021). "The Compared with adjacent non-tumorous tissues, we found a higher level of EIF3H, IGF2BP2, IGF2BP3, KIAA1429 in all six pancreatic tumor tissues, LRPPRC was overexpressed in five pancreatic tumor tissues, while the expression of METTL3 decreased in four pancreatic tumor tissues." (PMID 34332578, 2021). "Notably, real-time PCR revealed that METTL3, METTL14, and WTAP were upregulated in pancreatic cancer tissues compared with adjacent, healthy tissues." (PMID 32843065, 2020). "Here, the authors show that cigarette smoke promotes the maturation of oncogenic primary miR-25 due to METTL3 hypomethylation, and mature miR-25 suppresses PH domain leucine-rich repeat protein phosphatase 2, resulting in oncogenic AKT activation in pancreatic cancer." (PMID 31015415, 2019). "Furthermore, we analyzed the effects on EMP1 mRNA stability after METTL3 knockdown or overexpression and showed that overexpression of METTL3 in pancreatic cancer cells increased the stability of EMP1 mRNA, and consistently, the stability of EMP1 mRNA was inhibited after METTL3 knockdown." (PMID 41285728, 2025). "In general, our findings show that the downregulation of METTL3 suppresses virus replication by enhancing antiviral signaling in multiple pancreatic cancer cell lines and a nonmalignant pancreatic cell line, with JAK/STAT signaling being a critical factor in this process in PDAC cell lines." (PMID 40214229, 2025). "Therefore, we speculate that METTL3 can regulate SMS mRNA m6A methylation and be recognized by IGF2BP3 to further affect the prognosis of pancreatic cancer." (PMID 36276112, 2022). "Therefore, METTL3 and IGF2BP3 may play key roles in the m6A modification of SMS and pancreatic cancer progression." (PMID 36276112, 2022). "Therefore, we further explored the role of METTL3 and IGF2BP3 on pancreatic cancer cell." (PMID 36276112, 2022). "Therefore, the highly expressed SMS protein in pancreatic cancer may be related to the expression of METTL3 and IGF2BP3, and the expression of METTL3 and IGF2BP3 related to the migration and invasion of pancreatic cancer." (PMID 36276112, 2022). "However, the relevance of this network in pancreatic cancer has not yet been demonstrated, despite the critical role that METTL3 plays in pancreatic cancer." (PMID 32659892, 2020).
pancreatic cancer (continued). "A recent preclinical study shows that methyltransferase-like 3 (METTL3), an RNA m6A methyltransferase, is involved in the chemo- and radioresistance in pancreatic cancer cells, although it does not show any effect on the morphology and proliferation of the cells." (PMID 31540286, 2019).
liver cancer (114 papers, 2018 to 2026). An epithelial or non-epithelial malignant neoplasm that arises from the liver. "METTL3 governs the m6A modification of Frizzled‐10, increasing its expression in liver cancer stem cells and activating the β‐catenin and yes‐associated protein 1 (YAP1) signaling pathways." (PMID 39802639, 2025). "Together, results showed that both SRC and METTL3 were associated with worse survival of liver cancer patients." (PMID 40612868, 2025). "We demonstrated that c-Src kinase promoted liver cancer development, and the expression of SRC (encodes c-Src kinase) was positively correlated with METTL3 in liver cancer cases." (PMID 40612868, 2025). "It has been shown that METTL3 is elevated in many cancer types (including liver cancer) and associated with poor prognosis." (PMID 40103332, 2025). "METTL3 upregulation is associated with chemoresistance in breast and liver cancer due to metabolic reprogramming inside the cells." (PMID 39661414, 2024). "METTL3 is associated with the function of m6A modification, we therefore detected the m6A level in liver cancer samples and discovered that the level of m6A in cancer tissues was significantly up‐regulated as compared with the normal tissues (p < 0.001)." (PMID 35348293, 2022). "In liver cancer, changes in the m6A levels are caused by increased METTL3 and/or METTL14 expression." (PMID 35155557, 2022). "Some researchers have proposed that, as in liver cancer, new risk signatures constructed from 5 m6A-related genes (METTL3, METTL14, KIAA1429, ALKBH5 and YTHDF1) can be used as independent prognostic factors for PAAD." (PMID 34246319, 2021). "In summary, this study proposed a potential regulatory mechanism involving UBC9, SUMOylated Mettl3, and Snail in HCC progression, suggesting Mettl3 SUMOylation as a promising diagnostic and therapeutic target for liver cancer treatment." (PMID 32483411, 2020). "In liver cancer, high expression of writer, reader, and eraser proteins was associated with poor survival except METTL3, YTHDF3 and ALKBH5." (PMID 32863943, 2020). "METTL3 is overexpressed in hepatocarcinoma cells, and its overexpression is associated with a poor prognosis of liver cancer patients." (PMID 31808521, 2019). "In the present research, we performed in vitro and in vivo experiments to examine whether the effect and mechanism of miR‐589‐5p on liver cancer was associated with the METTL3‐mediated m6A methylation." (PMID 35348293, 2022). "Therefore, the MeRIP assay was performed, and for the first time, we further confirmed the association between m6A modification and METTL3 in liver cancer." (PMID 35348293, 2022). "However, it remains unclear if c-Src is associated with the METTL3-regulated mechanism in liver cancer." (PMID 40612868, 2025). "Since SUMOylation-deficient Mettl3 limited Snail accumulation, Snail expression was increased in the Mettl3-KR mutant-expressing group, which showed that Snail overexpression antagonized the suppression of wound healing through Mettl3 SUMOylation deficiency in liver cancer cells." (PMID 32483411, 2020). "Hepatitis B virus X‐interacting protein (HBXIP) is upregulated in liver cancer tissues and mediates the METTL3‐induced metabolic reprogramming and malignant behavior of HCC cells, accelerating tumor progression." (PMID 39802639, 2025). "Sorafenib, a targeted therapy for liver cancer, modulates METTL3, which subsequently affects FOXO3's role in autophagy." (PMID 39791162, 2025). "In this study, our in vivo experiments found that METTL3 induced the growth of mouse liver cancer tumors and induced lung metastasis of tumors by upregulating the m6A methylation level of BFSP1 mRNA, which was similar to the results of previous studies." (PMID 40097750, 2025).